CTLA4 (cytotoxic T-lymphocyte associated protein 4)
Diseases named in the same sentence as CTLA4 in open-access papers (continued):
Sharing a sentence is not in itself a finding about the gene and the disease.
cancer (continued). "The most commonly used class of cancer immunotherapy is immune checkpoint inhibitors (ICI) including block cytotoxic T-lymphocyte-associated protein 4 (CTLA-4), programmed cell death protein 1 (PD-1), or programmed death-ligand 1 (PD-L1)." (PMID 36936960, 2023). "Most extensively studied immune checkpoint receptors for cancer therapy are cytotoxic T-lymphocyte-associated antigen 4 (CTLA-4) and PD-1." (PMID 37970206, 2023). "Along with the extensive studies on CTLA-4 and PD-1/PD-L1 immune checkpoints, more and more immune checkpoints that can be blocked to associate with the therapeutic treatment of cancer have been found." (PMID 37106400, 2023). "Immune checkpoint inhibitors (ICIs), which inhibit programmed cell death 1 (PD-1) or programmed cell death 1 ligand 1 (PD-L1) and cytotoxic T lymphocyte-associated protein 4 (CTLA-4), have shown success in treating many cancers." (PMID 38066642, 2023). "Inhibition of the programmed cell death protein 1 (PD-1) and cytotoxic T-lymphocyte-associated protein 4 (CTLA-4) immune checkpoints has led to new immunotherapies against cancer." (PMID 36713082, 2023). "Monoclonal antibodies targeting cytotoxic T lymphocytes‐associated antigen 4 (CTLA4), programed death‐1 (PD‐1) receptor, and its ligand (PD‐L1) have achieved clinical success in some cancers." (PMID 36030492, 2023). "Despite their beneficial effects, systemic butyrate and propionate appear to limit the antitumor activity of CTLA-4 blockade in hosts with cancer and are associated with a higher proportion of Tregs." (PMID 36982144, 2023). "Following antibiotic treatment and recolonization with B. fragilis, Bacteroides thetaiotaomicron, Burkholderia cepacia, or a combination led to improved anti-CTLA-4 treatment efficacy, with B. fragilis also being implicated in anti-cancer immune response." (PMID 37498047, 2023). "Immune checkpoint blockade with monoclonal antibodies targeting the programmed death-ligand 1 (PD-L1)/programmed cell death 1 (PD-1) pathway or cytotoxic T lymphocyte-associated antigen 4 (CTLA-4) prolonged patient survival, considering many cancer types." (PMID 37627082, 2023). "Immune Checkpoint Inhibitors (ICIs) targeting the Cytotoxic T Lymphocyte-associated antigen 4 (CTLA-4) or Programmed cell death protein 1 (PD-1) pathways have demonstrated early success in treating various cancers." (PMID 38187373, 2023). "Together with cytotoxic T-lymphocyte-associated protein 4 (CTLA-4), PD-1 has been found to be the most reliable drug target in the treatment of advanced cancers." (PMID 37834467, 2023). "Other immune checkpoint receptors, such as cytotoxic T-lymphocyte-associated protein 4 (CTLA-4), have also been gaining more attention for use in monotherapy or in conjunction with other immunotherapies or conventional cancer therapeutics." (PMID 36980527, 2023). "Immune checkpoint inhibitors block the interaction between immune checkpoints, such as programmed cell death protein 1 (PD-1) and cytotoxic T-lymphocyte-associated antigen 4 (CTLA-4), and their corresponding ligands on cancer cells." (PMID 37425564, 2023). "Pan-cancer analysis revealed that most of the current clinical immune-related biomarkers, including PD-L1 and CTLA4, were associated with OSGIN2." (PMID 37031243, 2023). "CTLA-4 has two major isoforms generated by alternative splicing, namely sCTLA-4 and mCTLA-4, which are expressed in tumor cells and implicated in cancer immunosurveillance escape." (PMID 37630236, 2023). "Higher TIDE prediction scores are linked with worse immunotherapy response and unfavorable survival outcomes under anti-programmed cell death 1 receptor (PD1) and anti-cytotoxic T lymphocyte-associated protein 4 (CTLA4) therapies in pan-cancer." (PMID 36968603, 2023). "Checkpoint inhibitors, such as programmed cell death protein 1 (PD-1) and cytotoxic T-lymphocyte-associated protein 4 (CTLA-4) inhibitors, have shown remarkable success in treating various cancers." (PMID 37686159, 2023).
cancer (continued). "ICB therapeutics targeting programmed cell death 1/ligand 1 (PD-1/PD-L1) and cytotoxic T lymphocyte associated protein 4 (CTLA-4) have shown efficacy in a variety of T cell–inflamed cancers." (PMID 36918943, 2023). "The single nucleotide polymorphisms (SNPs) in the promoter region of the cytotoxic T-lymphocyte antigen-4 (CTLA-4) gene are directly associated with the progression and onset of various human cancers." (PMID 38186404, 2023). "The discovery that programmed cell death protein 1 (PD-1) and cytotoxic T-lymphocyte-associated protein 4 (CTLA-4) expressed on the surface of T cells act as a “brake” in immune function led to an approach to target cancer." (PMID 35763108, 2023). "Two predominant immune checkpoint pathways that have been extensively studied in cancers are those associated with cytotoxic T-lymphocyte-associated protein 4 (CTLA-4) and programmed cell death protein 1 (PD-1)." (PMID 37762648, 2023). "Among cancer therapies, immune checkpoint inhibition using antibodies against programmed cell death protein 1 (PD-1), PD-1 ligand (PD-L1), or cytotoxic T-lymphocyte-associated protein 4 (CTLA-4) has led to impressive clinical responses in patients." (PMID 38022587, 2023). "Several epidemiological studies were conducted for the investigation of the correlation of the CTLA-4 rs11571317 −658 C>T polymorphism and their chances of cancer progression." (PMID 38186404, 2023). "The clinical trials of the immune checkpoint inhibitors as programmed cell death protein 1 (PD-1) and cytotoxic T lymphocyte-associated protein 4 (CTLA4) have promising results with other cancer types, whereas they have been unsuccessful in PDAC6,8." (PMID 37945567, 2023). "The FDA has approved six types of immune checkpoint inhibitors (ICIs) for cancer therapy since 2011, including targeting cytotoxic T lymphocyte-associated protein 4 (CTLA-4), programmed death-1 (PD-1), and programmed death-ligand 1 (PD-L1)." (PMID 36969851, 2023). "Specific immune checkpoints such as cytotoxic T-lymphocyte-associated protein 4 (CTLA-4) and programmed cell death protein 1 (PD-1) were identified as critical regulatory pathways that inhibit the T-cell response to cancer cells." (PMID 38022633, 2023). "For example, combined ICB with drugs targeting both the PD-1 pathway along with the cytotoxic T-lymphocyte-associated protein 4 (CTLA-4) checkpoint has demonstrated increased efficacy in several cancers, albeit with increased toxicity." (PMID 37500647, 2023). "Cytotoxic T-lymphocyte-associated antigen 4 (CTLA-4), a surface receptor on T lymphocytes, can also be used as an immune checkpoint inhibitor to treat cancer, similar to PD-L1." (PMID 37305384, 2023). "Immune-checkpoint inhibitors, such as antibodies targeting PD-1 (programmed cell death protein 1) and CTLA-4 (cytotoxic T-lymphocyte-associated protein 4), have shown success in unleashing the immune system against cancer cells." (PMID 37345057, 2023). "A recent study suggested that cancer-cell-derived IL-33 is necessary to synergize with Cytotoxic T-Lymphocyte-Associated protein 4 (CTLA-4) or Programmed Cell Death 1 (PD-1) monoclonal antibodies (mAbs) to enhance antitumor efficacy." (PMID 37762328, 2023). "Two of the most studied immune checkpoint molecules are cytotoxic T lymphocyte-associated protein 4 (CTLA-4) and programmed cell death protein 1 (PD-1), the latter binding to its ligand PD-L1 on cancer cells and immune cells." (PMID 37240052, 2023). "These agents target immune-cell-surface checkpoint proteins, including the cytotoxic T-lymphocyte-associated protein-4 (CTLA4) and the programmed death-1/programmed death ligand-1 (PD-1/PD-L1), which inhibit anti-cancer immune responses." (PMID 37046745, 2023). "Although CTLA-4 is localized in the promoter region for the risk of cancers, their presence, and functional effects of CTLA-4 rs11571317 −658 C>T polymorphisms in the population of Saudi Arabia in any types of cancers have not yet been elucidated." (PMID 38186404, 2023).
cancer (continued). "Anti-Cytotoxic T-Lymphocyte Associated protein 4 agents, such as ipilimumab, are widely applied to various cancers." (PMID 37072549, 2023). "Altered expression of ICIs underlies cancer evasion from immune surveillance, and immunotherapies that targeted CTLA-4 and PD-1 were effective against a variety of cancers." (PMID 37671150, 2023). "Blocking programmed cell death protein 1 (PD-1)/PD-1 ligand 1 (PD-L1) and cytotoxic T lymphocyte-associated protein 4 (CTLA-4), immune checkpoints using antibodies is a highly effective immunotherapeutic strategy for cancer." (PMID 36508191, 2023). "Immune checkpoints, including programmed cell death protein 1 (PD-1), programmed cell death 1 ligand 1 (PD-L1) and cytotoxic T-lymphocyte-associated protein 4 (CTLA-4) have proven to be suitable targets for cancer immunotherapy." (PMID 36675241, 2023). "Monoclonal antibodies directed toward CTLA-4 have been found to provide an immunotherapeutic effect against cancer (CITE), however, they are also associated with inducing severe immunotherapy-related adverse events (irAE)." (PMID 37828948, 2023). "Therapies that target immune checkpoint markers, such as monoclonal antibodies that block PD-L1 and CTLA-4, have shown promise in treating a variety of cancers, particularly those that are associated with a high level of immune checkpoint marker expression." (PMID 38085674, 2023). "This groundbreaking approach, rooted in historical milestones like “Coley’s toxins” and, later, the identification of cytotoxic T-lymphocyte-associated antigen 4 (CTLA-4), has consistently showcased the potential to redefine cancer treatment paradigms." (PMID 38136402, 2023). "Blockade of inhibitory receptors such as cytotoxic T-lymphocyte associated protein 4 (CTLA-4) or the Programmed cell death 1 (PD-1)/PD-L1 axis on T lymphocytes is another major strategy applied in cancer immunotherapy." (PMID 37936122, 2023). "At present, immune checkpoint therapy is used as a cancer therapy in addition to radiation, chemotherapy, and surgery and includes the blocking of cytotoxic T-lymphocyte-associated protein 4 (CTLA-4) and programmed cell death protein 1 (PD-1)." (PMID 37078359, 2023). "They express inhibitory receptors, such as PDCD1, TIM-3, TIGIT, LAG-3 and cytotoxic T-lymphocyte-associated protein 4 (CTLA4), which induce T-cell exhaustion and prevent T-cell activation; however, cancer cells utilize these receptors to evade T-cell attacks." (PMID 36979400, 2023). "At present, the immune checkpoint inhibitors (ICIs) including programmed cell death protein 1 (PD-1) or its ligand 1 (PD-L1), and cytotoxic T-lymphocyte-associated protein 4 (CTLA-4) have been approved for certain types of cancer." (PMID 36865925, 2023). "In their study, curcumin-evoked inhibition of CSN5 caused a decrease in PD-L1 expression in cancer cells, sensitizing them to anti-CTLA4 therapy." (PMID 36902456, 2023). "Programmed cell death protein 1 (PD1 and its ligand PDL1) and cytotoxic T lymphocyte-associated antigen-4 (CTLA-4) are the main immune checkpoints involved in cancer therapy." (PMID 36982500, 2023). "The use of anti-programmed death-ligand 1 (anti-PD-L1), programmed death-1 (anti-PD-1) and cytotoxic T-lymphocyte-associated protein 4 (anti-CTLA-4) has been shown to increase life expectancy in patients with certain cancers." (PMID 37794509, 2023). "The cytotoxic T lymphocyte-associated protein 4 (CTLA-4) and the programmed cell death 1 (PD-1) are the most known pathways in cancers." (PMID 36658300, 2023). "The most well-known ICMs in cancer are the programmed cell death 1 (PD-1), with its two ligands, PD-L1 and PD-L2, and cytotoxic T lymphocyte-associated protein 4 (CTLA-4), which also has two ligands, CD80 and CD86." (PMID 37958474, 2023).
cancer (continued). "Increased RAMP1 expression was strongly associated with the upregulation of lymphocyte activation gene 3 (LAG3), vascular endothelial growth factor B (VEGFB), and cytotoxic T-lymphocyte-associated protein 4 (CTLA-4) across multiple cancer types." (PMID 37796823, 2023). "Currently, several antibodies against the cytotoxic T lymphocyte-associated antigen-4 (CTLA-4) or programmed cell death 1 (PD-1)/programmed cell death 1 ligand 1 (PD-L1) signaling pathway are approved for the treatment of various cancers." (PMID 37860188, 2023). "Patients with a wide variety of cancers benefit from antibodies that target immunological checkpoints, such as cytotoxic T-lymphocyte-associated protein-4 (CTLA-4), PD-1, and PD-L1." (PMID 37190310, 2023). "Intrinsic immunosuppression underlies the efficacy of the checkpoint inhibitors programmed cell death protein 1 (PD-1) and cytotoxic T-lymphocyte associated protein 4 (CTLA-4) in many cancer types." (PMID 37654497, 2023). "A combination of anti–CTLA-4 plus anti–PD-1/PD-L1 is the most effective cancer immunotherapy but causes high incidence of immune-related adverse events (irAEs)." (PMID 35239514, 2022). "The FDA have approved immune checkpoint inhibitors (ICIs) against cytotoxic T-lymphocyte-associated antigen (CTLA-4), programmed cell death receptor 1 (PD-1), and programmed cell death 1 ligand 1 (PD-L1) for treatment in many types of cancers." (PMID 35864548, 2022). "Recently, the development of immune checkpoint inhibitors (ICIs) targeting cytotoxic T lymphocyte-associated antigen 4 (CTLA-4) and programmed death 1/programmed death ligand 1 (PD-1/PD-L1) raises new hope for cancer patients." (PMID 36424540, 2022). "In 1987, the cytotoxic T lymphocyte-associated protein 4 (CTLA-4) was discovered as the first immune checkpoint, thus opening the door to cancer immunotherapy." (PMID 35879796, 2022). "Especially blocking of the cytotoxic T lymphocyte-associated protein-4 (CTLA-4), the programmed death (PD)-1 T cell receptor, and its ligand PD-L1 have shown to be promising targets to activate the immune system to attack cancer cells." (PMID 35836932, 2022). "Immune checkpoint inhibitors (ICIs) targeting the programmed death-1 (PD-1)/programmed death-ligand 1 (PD-L1) and cytotoxic T-lymphocyte-associated protein 4 (CTLA4) pathways are among the newest entrants into the arsenal for cancer treatment." (PMID 35290407, 2022). "Programmed cell death protein 1 (PD-1), programmed cell death 1 ligand 1 (PD-L1) and cytotoxic T lymphocyte associated protein 4 (CTLA-4) checkpoint inhibitors are important milestones in the drug development for cancer therapy." (PMID 35251028, 2022). "The development of cancer immunotherapy in clinical practice initiated from immune checkpoint inhibitors (ICIs), especially ipilimumab, an anti-cytotoxic T lymphocyte-associated antigen 4 (CTLA-4) monoclonal antibody." (PMID 35849585, 2022). "Immune checkpoint inhibitors (ICIs), including anti-programmed cell death 1 (PD-1), anti-programmed cell death ligand 1 (PD-L1), and anti-cytotoxic T lymphocyte-associated protein 4 (CTLA-4), are revolutionary progress in cancer therapy." (PMID 35912168, 2022). "Cytotoxic T-lymphocyte-associated antigen 4 (CTLA-4) and programmed cell death protein 1 (PD-1), two clinically relevant targets for the immunotherapy of cancer, are negative regulators of T-cell activation and migration." (PMID 36428963, 2022). "The Rs231775 (+49) A/G polymorphism is one of the common SNPs in the CTLA-4 gene and has been extensively reported in many types of cancers." (PMID 35600409, 2022). "Recently, immune checkpoint treatments targeting programmed cell death 1/programmed cell death-ligand 1 (PD-1/PD-L1) and cytotoxic T-lymphocyte-associated antigen 4 (CTLA-4) have been rapidly developed as therapeutic approaches for cancer." (PMID 36567857, 2022).
cancer (continued). "Checkpoint inhibitors, such as anti-CTLA-4 (cytotoxic T-lymphocyte-associated protein 4) and anti-PD-1, have demonstrated efficacy in many cancer types." (PMID 35163730, 2022). "Programmed death 1 (PD-1), programmed death-ligand 1 (PD-L1), and cytotoxic T lymphocyte-associated protein 4 (CTLA-4) inhibitors are examples of monoclonal antibodies commonly used in cancer immunotherapy, particularly in advanced NSCLC." (PMID 36230736, 2022). "The field of cancer immunotherapy has been forever changed by ICIs that block immunological checkpoints such cytotoxic T lymphocyte-associated antigen 4 (CTLA-4), programmed death 1 (PD-1) and its ligand (PD-L1), and PD-1 ligand 2 (PD-L2)." (PMID 36685904, 2022). "In cancer immunotherapy, antibodies that interfere with the functions of immune checkpoint molecules such as Programmed cell death-1 (PD-1, encoded by Pdcd1) and Cytotoxic T-lymphocyte-associated protein 4 (CTLA-4) are administered to cancer patients." (PMID 35734392, 2022). "Prior studies indicated an association between interleukin 4 (IL-4) and cytotoxic T lymphocyte protein 4 (CTLA-4) gene polymorphisms in many types of cancers, including HCC that are either hepatitis B virus (HBV)- or hepatitis C Virus (HCV)-induced." (PMID 35525950, 2022). "Monoclonal antibodies (mAbs) targeting cytotoxic T lymphocyte-associated antigen 4 (CTLA-4) or the programmed cell death protein 1 pathway (PD-1/PD-L1) are already being applied clinically to treat a variety of human cancers, especially advanced solid tumors." (PMID 35292660, 2022). "Currently, programmed cell death protein 1 (PD-1) or its ligands PD-L1 and cytotoxic T-lymphocyte-associated protein 4 (CTLA-4) are approved for the treatment of cancer patients." (PMID 35699863, 2022). "In some cancers, overexpression of CTLA-4 has been found to be caused by promoter hypomethylation, which would increase the suppressive activity of Tregs and in turn reduce cancer immunity." (PMID 36428581, 2022). "Cancer immunotherapy with immune checkpoint blockade (ICB) targeting programmed cell death protein 1 (PD-1) or cytotoxic T lymphocyte-associated antigen 4 (CTLA-4) has revolutionized cancer treatment in different malignancies." (PMID 36139377, 2022). "The emergence of monoclonal antibodies (mAbs) against cytotoxic T-lymphocyte-associated antigen 4 (CTLA-4), programmed death 1 receptor (PD-1), and its ligand, PD-L1, has revolutionized the treatment landscape of cancer." (PMID 35251045, 2022). "The two latter ones (C. aerofaciens and F. prausnitzii) are also associated with clinical response to immunotherapy (anti-CTLA-4 or anti-PD-1 treatments) in cancer patients." (PMID 35418098, 2022). "Immunomodulators blocking cytotoxic T-lymphocyte-associated protein 4 (CTLA-4) and programmed cell death protein 1 (PD-1) or programmed death-ligand 1 (PD-L1) have improved the treatment of a broad spectrum of cancers." (PMID 35511238, 2022). "In most types of cancer, two immune checkpoints, programmed cell death protein 1 (PD-1) and cytotoxic T lymphocyte-associated protein 4 (CTLA-4), were observed with an upregulated expression on T cells in the TME." (PMID 35433427, 2022). "Programmed cell death protein 1 (PD-1) and cytotoxic T-lymphocyte-associated protein 4 (CTLA-4) are both signaling molecules commonly seen on activated T cells, and have been found to be effective immunotherapeutic targets in cancer." (PMID 36324574, 2022). "ICIs were developed against programmed cell death ligand 1 (PD-L1) on cancer cells, and the immune suppressive receptors programmed cell death 1 (PD-1) and cytotoxic T-lymphocyte-associated antigen 4 (CTLA-4) on cytotoxic T cells." (PMID 35844547, 2022). "Immune checkpoint inhibitors like programmed cell death 1 (PD-1) and cytotoxic T-lymphocyte-associated protein 4 (CTLA-4) are biological agents that help in boosting the immune system of the body to fight against cancer cells." (PMID 35600068, 2022).